AQP7 (aquaporin 7)
Description:
Aquaglyceroporins form homotetrameric transmembrane channels, with each monomer independently mediating glycerol and water transport across the plasma membrane along their osmotic gradient. Could also be permeable to urea. Mediates the efflux of glycerol, formed upon triglyceride hydrolysis, to avoid its accumulation in adipocytes and to make it available to other tissues. In the kidney, mediates the reabsorption of glycerol, preventing its loss in urine, again participating to energy homeostasis. In pancreatic beta cells, it also mediates the efflux of glycerol, regulating its intracellular levels (By similarity).
Synonyms: AQPap; AQP7L; AQP9; GLYCQTL
Tractability: Small molecule: a structure with a bound ligand is known. Antibody: UniProt places it where antibodies can reach, with high confidence; its Gene Ontology location is reachable by antibodies, with high confidence; UniProt predicts a signal peptide or a membrane-spanning region.
Gene: Protein-coding gene on chromosome 9 (33,383,179 to 33,402,682, reverse strand). Ensembl gene ENSG00000165269.
Subcellular location: Cell membrane; Cytoplasmic vesicle membrane; Lipid droplet
Subcellular location (Human Protein Atlas): Vesicles; Nuclear speckles; Nucleoplasm
Pathways (Reactome):
Transport of small molecules: Passive transport by Aquaporins; Transport of glycerol from adipocytes to the liver by Aquaporins
Gene Ontology:
Molecular function: glycerol channel activity; protein binding; urea transmembrane transporter activity; water channel activity; channel activity
Biological process: glycerol transmembrane transport; water transport; transmembrane transport; urea transmembrane transport
Cellular component: cell-cell junction; cytoplasm; plasma membrane; basolateral plasma membrane; cytoplasmic vesicle membrane; lipid droplet; membrane
Genetic constraint (gnomAD): Loss-of-function variants: 22 observed, 25.33 expected, observed/expected ratio (o/e) 0.87, 90% interval 0.62 to 1.24. The upper end of that interval is the gene's LOEUF score, 1.24, which puts it in group 5 of 6, group 1 being the genes least tolerant of losing a copy. Missense variants: 412 observed, 464.9 expected, observed/expected ratio (o/e) 0.89, 90% interval 0.82 to 0.96. Synonymous variants: 167 observed, 182.44 expected, observed/expected ratio (o/e) 0.92, 90% interval 0.81 to 1.04.
Homologues: Orthologues: chimpanzee AQP7 (97% identical), macaque AQP7 (96% identical), guinea pig Aqp7 (75% identical), dog AQP7 (72% identical), mouse Aqp7 (65% identical), rat Aqp7 (55% identical), tropical clawed frog aqp7 (42% identical), zebrafish aqp7 (42% identical), Caenorhabditis elegans aqp-2 (30% identical), Drosophila melanogaster Eglp1 (15% identical), Drosophila melanogaster Eglp2 (15% identical), Drosophila melanogaster Eglp4 (15% identical), and 1 more. Paralogues in human: AQP7B (93% identical), AQP3 (38% identical), AQP9 (34% identical), AQP10 (34% identical), AQP2 (23% identical), AQP6 (22% identical), MIP (22% identical), AQP4 (20% identical), AQP5 (20% identical), AQP1 (19% identical), AQP8 (18% identical).
Diseases named in the same sentence as AQP7 in open-access papers:
AQP7 is named in the same sentence as 70 diseases in open-access papers, as found by Europe PMC text mining. Sharing a sentence is not in itself a finding about the gene and the disease. The quoted sentences say what the papers report.
Obesity (50 papers, 2013 to 2026). Accumulation of substantial excess body fat. "Of note, single-nucleotide variations in the AQP7 gene were found to be associated with obesity and T2D." (PMID 40927981, 2026). "Of note, the reverse scenario of enhanced expression of AQP7 associated with diet-induced obesity in mice promotes BAT “whitening,” that is, conversion to a WAT phenotype with TG deposition, but the mechanism responsible for this process is not known." (PMID 40927981, 2026). "In humans, common variants in the promoter region of AQP7, linked to a reduced expression of AQP7 in the adipose tissue, have been associated with obesity and metabolic complications." (PMID 41203811, 2025). "Supporting this, Prudente and coworkers found an association between a single nucleotide polymorphism (SNP) in the promoter region of AQP7 and obesity." (PMID 39201693, 2024). "In contrast to the findings in this study, some studies have found that obesity is associated with a reduced expression of AQP7 in abdominal SAT." (PMID 39201693, 2024). "AQP7 has been associated with multiple disease states, including obesity, insulin resistance, and thyroid and breast cancers, indicating the potentially broad clinical application of an AQP7-selective modulator." (PMID 39123442, 2024). "Most of these studies point towards obesity being associated with a reduced expression of AQP7 in abdominal SAT when compared with lean controls." (PMID 39201693, 2024). "The SNP resulted in a reduced expression of AQP7 and the association with obesity was found only in women." (PMID 39201693, 2024). "The findings suggest the safety of this cardiac-protective strategy even when the AQP7 gene is downregulated due to obesity or missense mutations." (PMID 37691043, 2024). "Diet-induced obesity was associated with an increase in circulating glycerol levels as well as with an upregulation of AQP7 in BAT, which was strongly associated with the increase in the lipogenic factors Pparg2, Mogat2 and Dgat1." (PMID 36834823, 2023). "AQP7 deficiency in adipocytes increases glycerol kinase activity and accelerates triglyceride synthesis, ultimately leading to obesity." (PMID 38089606, 2023). "Altogether, these data suggest that dysregulated AQP7 expression is linked to dysregulated insulin secretion, thereof suggesting AQP7 as a potential therapeutic target for human obesity-associated type 2 diabetes." (PMID 37681902, 2023). "Further investigations are required to establish the suitability of the regulation of AQP7 in BAT as a therapeutic target for human obesity-associated type 2 diabetes." (PMID 36834823, 2023). "In turn, obesity leads to genetic polymorphism (A-953G SNP) causing underexpression of AQP7 in adipocytes." (PMID 34069293, 2021). "In a previous study, an association between obesity and a single-nucleotide-polymorphism in the promotor of AQP7 that causes a decreased transcription of the aqp7 gene was found in women only." (PMID 33193093, 2020). "Additional studies are required to deepen the current knowledge concerning the impact of AQP7 loss-of-function mutations or single nucleotide polymorphism in diabetes, obesity and metabolic syndrome." (PMID 31614661, 2019). "Single nucleotide polymorphisms in the AQP7 gene have been associated with obesity and/or type 2 diabetes in Caucasians and with type 2 diabetes in the Chinese Han population." (PMID 31614661, 2019). "In all, the potential role of AQP7 deficiency in increased susceptibility to development of obesity seems most evident among women, which pinpoints that future studies should be performed in a gender-specific manner." (PMID 29300344, 2018). "The proposed linkage between AQP7 deficiency and obesity with secondary development of insulin resistance has also been investigated in human studies." (PMID 29300344, 2018). "AQP7 deficiency has been linked to triglycerides (TG) accumulation in adipose tissue, adipocyte hypertrophy, adult onset obesity, and insulin resistance." (PMID 30598999, 2018).
Obesity (continued). "AQP7-KO mice display a clear phenotype of adult-onset obesity and hyperinsulinemia, but the impact of AQP7 loss-of-function homozygous mutations in human obesity and diabetes remains controversial." (PMID 29675407, 2018). "Further studies are required to analyze the real impact of AQP7 gene variants in the onset of obesity and type 2 diabetes." (PMID 29675407, 2018). "A SNP (A953G) in the promoter of AQP7 that causes decreased transcriptional activity is associated with obesity and secondary development of T2D in women, thus to some extent mimicking the observations made in AQP7 KO mice." (PMID 29300344, 2018). "The downregulation of AQP7 was also reported to increase susceptibility of obesity by promoting lipid accumulation in the adipose tissue." (PMID 27703473, 2016). "In this sense, Aqp7 gene disruption leads to obesity, and Aqp9 deficiency is related to a defective hepatic glycerol metabolism in mice." (PMID 26594198, 2015). "AQP7 deficient mice show marked adipocyte hypertrophy and develop adult-onset obesity and insulin resistance." (PMID 23382902, 2013). "Some studies have also found AQP7-promoter variants in obesity." (PMID 39456161, 2024). "In VAT, however, obesity has been associated with an increased expression of AQP7, which could suggest a depot-specific regulation to reduce TG accumulation in VAT." (PMID 39201693, 2024). "This suggests that the lower degree of obesity caused by short-term HFD in female mice compared to male mice may be linked to the elevated expression of AQP7 in the adipocytes of female mice." (PMID 39456161, 2024). "Thus, the altered expression of AQP7 in WAT is associated with obesity and metabolic disorders, such as type 2 diabetes." (PMID 36834823, 2023). "In addition, single nucleotide polymorphisms in the Aqp7 gene have been linked to obesity and/or type 2 diabetes in Caucasians and with type 2 diabetes in the Chinese Han population." (PMID 37681902, 2023). "AQP7 deficiency results in reduced membrane glycerol permeability which leads to increased triglyceride accumulation inside adipocytes and adipocyte hypertrophy contributing to the onset of obesity." (PMID 34069293, 2021). "An additional effect may be exerted by the underexpression of aquaporin 7 (AQP7) in adipocytes, as a consequence of human AQP7 genetic polymorphism (the A-953G SNP causing AQP7 down-regulation), which is related to obesity." (PMID 32992734, 2020). "However, since leptin has been shown to reduce the AT AQP7 abundance the effect of obesity in the setting of leptin/leptin receptor deficiency is difficult to interpret." (PMID 33193093, 2020). "Direct effects of variants in AQP7 on the heart are unknown, but obesity and diabetes themselves may have various adverse effects on cardiac (electrophysiological) function." (PMID 31027200, 2019). "A common polymorphism in the promoter region of the human AQP7 gene, resulting in AQP7 downregulation, is pathogenic for obesity and/or type 2 diabetes, while missense mutations in AQP7 are associated with an inability to increase the plasma glycerol during exercise." (PMID 31027200, 2019). "Furthermore, subjects with a genetic variant of AQP7 featuring a deletion of guanine at position 953 (−953G) had an increased risk of obesity and/or T2DM." (PMID 29914059, 2018). "AQP7 is expressed in adipose tissue where it facilitates the efflux of glycerol, and AQP7 deficiency has been linked to increased glycerol kinase activity and triglyceride accumulation in adipose tissue, leading to obesity and secondary development of insulin resistance." (PMID 29300344, 2018). "Moreover, an association between obesity and a single nucleotide polymorphism (SNP) in the promotor of AQP7 causing a decrease transcription of the aqp7 gene was found only among women." (PMID 29300344, 2018). "Such distinct findings could account for the differences observed in the susceptibility of AQP7 knockout mice of distinct genetic background to developing obesity." (PMID 29186031, 2017).
Obesity (continued). "Chronic leptin administration in male leptin-deficient ob/ob mice down-regulated adipose AQP3 and AQP7 at the same time as it upregulated hepatic AQP9 in parallel with the improvement of obesity and hepatosteatosis observed in this genetically obese animal model." (PMID 26594198, 2015). "Indeed, an adipocyte volume increase in obesity was associated to AQP7 depletion in knock-out mice; however, in our study, the increased non-osmotic volume was not matched by an accompanying increased cell volume." (PMID 24376702, 2013). "The site of AQP7 expression, exclusively in endothelial cells or in endothelial cells and adipocytes, could account for the susceptibility of mice to develop obesity." (PMID 30042691, 2018). "From a clinical point of view, the possibility of regulating the pancreatic AQP7 function, by the upregulation of AQP expression or possibly by gene transfer in rare cases of loss-of-function mutations of the AQP7 gene, may also be beneficial in obesity, insulin resistance and type 2 diabetes." (PMID 29675407, 2018). "Moreover, Aqp7 KO mice exhibited whole body insulin resistance associated with obesity." (PMID 29186031, 2017). "All together, data obtained in murine KO models for AQP7 gene have suggested a pivotal role of AQP7 in maintaining the normal adiposity and that its altered expression might be implicated in the susceptibility to obesity and related disorders." (PMID 23382902, 2013). "-Carboxymethyl chitin activates AMPK signaling.-Aquaporin-7 regulation reduces triglyceride accumulation.-Anti-obesity potential through adipogenesis inhibition." (PMID 40004938, 2025). "Genetic deletion of AQP7 in mice resulted in glycerol accumulation, adipocyte hypertrophy, adult-onset obesity, insulin resistance and altered glycerol metabolism." (PMID 41203811, 2025). "In this study, we combined human, mouse, and in vitro cellular models to characterize the role of AQP7 in adipose tissue regulation, metabolism, and obesity-related dysfunction." (PMID 41203811, 2025). "The correlation between reduced expression of AQP7 in the adipose tissue and increased BMI was observed in humans, supporting the link between AQP7 downregulation, obesity, and metabolic disturbances." (PMID 41203811, 2025). "As a result, the regulatory mechanisms that govern the differential expression of AQP7 in adipose tissue in obesity necessitate further exploration." (PMID 39456161, 2024). "Studies have indicated that the level of AQP7 mRNA expression in prepubertal obese children carrying this mutant gene is lower than that of other prepubertal children with obesity, although their fasting insulin concentration is normal." (PMID 39456161, 2024). "The expression by adipocyte AQP7 of obesity at different ages also appears to be altered to different degrees, and even the AQP7 isoforms presented in adipose tissue vary among obesity patients of different ages." (PMID 39456161, 2024). "Many human studies investigating the expression of AQP7 in WAT in relation to obesity have analyzed mRNA levels in abdominal subcutaneous adipose tissue (abdominal SAT) and/or visceral adipose tissue (VAT) in mixed-gender cohorts." (PMID 39201693, 2024). "Another mouse analysis showed that AQP7 mRNA levels in the quadriceps femoris muscles were significantly higher in mice with diet-induced obesity than in control chow-fed mice." (PMID 37691043, 2024). "It was found that the promoter region of AQP7 exhibited hypomethylation at three CpG sites in diet-induced-obesity rat models." (PMID 39456161, 2024). "Its carboxymethylated derivative (CM-chitin) similarly demonstrated the potential to manage obesity by enhancing AQP7 expression." (PMID 39456161, 2024). "Immuno-histochemical analysis of the muscles of mice with diet-induced obesity showed enhanced expression of AQP7 at the myofiber surface membranes, suggesting that AQP7 facilitated the secretion of glycerol from myocytes." (PMID 37691043, 2024).
Obesity (continued). "In women with upper-body obesity, there were statistically significant differences in AQP7 expression between adipose tissue depots, as determined by non-parametric one-way ANOVA (p = 0.035)." (PMID 39201693, 2024). "Other methods, such as massage and sleeve gastrectomy, have also been found to have some effect on AQP7 in obesity tissues as a way to reduce fat accumulation." (PMID 39456161, 2024). "The gene expression of AQP7 in different animal species and organs during obesity should be further investigated." (PMID 37691043, 2024). "More interestingly, multiple AQP7 isoforms were exhibited in the adipocytes of children and adolescents with obesity." (PMID 39456161, 2024). "Similar to HSL, the reduced AQP7 expression in abdominal SAT reported in other studies was performed in individuals with obesity that generally had a higher BMI (35 kg/m2 or >40 kg/m2) than the mean BMI of the women included in this study." (PMID 39201693, 2024). "Aquaporin 7 (AQP7), a transporter protein present in the plasma membrane of adipocytes, is positively correlated with the degree of obesity." (PMID 38089606, 2023). "Aquaglyceroporin 7 (AQP7) facilitates glycerol flux across the plasma membrane with a critical physiological role linked to metabolism, obesity, and associated diseases." (PMID 36737436, 2023). "This process is reversible by cold exposure and bariatric surgery, thereby suggesting the potential of targeting BAT AQP7 as an anti-obesity therapy." (PMID 36834823, 2023). "Studies with aqp7−/−-null mice showed a three-fold reduction in glycerol release into the bloodstream, leading to adult-onset obesity and insulin resistance; the knockdown of AQP7 in mouse 3T3-L1 adipocytes resulted in two-fold lower glycerol secretion." (PMID 35163313, 2022). "It has been reported that adipose Aqp7 and Aqp9 gene expression was increased by diet-induced obesity in mice." (PMID 34360801, 2021). "This may be due to the expression of AQP7 in adipose tissue where it facilitates the efflux of glycerol, and AQP7 deficiency has been linked to increased glycerol kinase activity and triglyceride accumulation in adipose tissue, leading to obesity and secondary development of insulin resistance." (PMID 32309443, 2020). "The downregulation of AQP7 expression is closely related to the occurrence of type 2 diabetes and obesity." (PMID 32821266, 2020). "Our results indicate that ginsenoside Rb1 can promote lipid transport and ameliorate obesity by upregulating AQP7 through the PPARγ pathway." (PMID 32821266, 2020). "In different mouse models of obesity, a coordinated upregulation of AQP7 and AQP9 mRNA has been reported in male mice." (PMID 33193093, 2020). "In fact, although all aquaglyceroporins (AQP3, 7, 9, and 10) are expressed in human adipose tissue, AQP7 expression increases along with white adipocyte differentiation and has been reported to be involved in obesity." (PMID 31963489, 2020). "Like for AQP7, leptin has been shown to regulate hepatic AQP9 abundance, thus complicating the interpretation of the effect of obesity on AQP9 abundance in leptin deficient mice." (PMID 33193093, 2020). "AQP7 KO mice are seen to have higher levels of fat than wild type controls and this is thought to be a therapeutic target for obesity." (PMID 30934923, 2019). "Due to AQP7’s expression, especially in β-cells, AQP7 became a protein of interest in light of pathologies affecting endocrine pancreas, in particular diabetes, obesity and metabolic syndrome." (PMID 31614661, 2019). "AQP7 and AQP9 coordinated function is crucial for energy homeostasis and deregulation has been implicated in obesity and diabetes." (PMID 29977890, 2018). "In adipose tissue, AQP7 deficiency is linked to increased TG accumulation and development of obesity; however, when considering targeting of AQP7 in anti-obesity therapy, the wide range of tissues where AQP7 is expressed should be taken into account." (PMID 29300344, 2018).